MYC (MYC proto-oncogene, bHLH transcription factor)
Diseases named in the same sentence as MYC in open-access papers (continued):
Sharing a sentence is not in itself a finding about the gene and the disease.
breast cancer (continued). "Loss or down-regulation of the Ecadherin gene CDH1 at 16q22.1 is associated with breast cancer proliferation and invasion, MYC is an effective tumorigenic activator, a transcription factor, and a key regulator of cell growth, differentiation, and apoptosis." (PMID 32318558, 2020). "Given the association of disease-free survival and MYC scores of primary breast cancer, we predicted that higher MYC scores would also be associated with worse survival in metastatic breast cancer." (PMID 33143224, 2020). "In breast cancer patients, high MYC expression is associated with endocrine therapy resistance and poor survival outcomes." (PMID 32340192, 2020). "In a query of The Cancer Genome Atlas (TCGA) database, we found that PIK3CA was the most frequently mutated gene in breast cancer, while MYC and CDKN2A/B were the genes most frequently associated with amplifications and deletions, respectively." (PMID 32498332, 2020). "Given that high MYC scores were associated with high cell proliferation, it was expected that higher scores would also be associated with clinically aggressive breast cancer." (PMID 33143224, 2020). "Next, we investigated how flavopiridol and dinaciclib lead to preferential loss of BRD4/NSD3, impacting the oncogene MYC, thereby, promoting cell cycle arrest in breast cancer." (PMID 32412527, 2020). "As expected, in contrast to ATR, we observed that low ATM was linked to aggressive phenotypes in MYC overexpressed breast cancers, including in ER+ tumours." (PMID 30746633, 2019). "Suppose we are interested in identifying DNA promotorial regions bound by the MYC transcription factor and that present somatic mutations in breast cancer patients with tumor recurrence." (PMID 31820804, 2019). "Implementation of FPPa-OmoMYC and its derivatives in future clinical trials is expected for the treatment of MYC-associated breast cancer, such as basal-like TNBC." (PMID 31013830, 2019). "In ER + breast cancer, similarly, MYC overexpressed tumours with high ATR levels are associated with worse survival (p < 0.001) including in patients who received endocrine therapy." (PMID 30746633, 2019). "Here, we investigated the extent to which TEs contributed binding sites for three breast cancer-associated TFs (C/EBPβ, E2F1 and MYC) in breast cancer." (PMID 31061680, 2019). "High serum epinephrine is associated with poor prognosis and activated LDHA/USP28/MYC/SLUG signaling axis in breast cancer patients." (PMID 30688660, 2019). "Iterative mouse modeling and comparative oncogenomics analysis show that MYC-overexpression strongly reshapes the CNA landscape of BRCA1-deficient mammary tumors and identify MCL1 as a collaborating driver in these tumors." (PMID 30674894, 2019). "In ER+ breast cancer, similarly, MYC overexpressed tumours with low ATM levels were associated with worse survival (p < 0.001) including in patients who received endocrine therapy." (PMID 30746633, 2019). "The potent MYC oncoprotein is deregulated in many human cancers, including breast carcinoma, and is associated with aggressive disease." (PMID 31350286, 2019). "Similar genomic hotspots of germline and somatic aberration alignments have been noted in breast cancer where tandem duplications were found to peak where two germline susceptibility loci were present on MYC." (PMID 29560112, 2018).
breast cancer (continued). "Of importance, overexpression of MYC in luminal breast cancer cell lines also caused downregulation of ML-specific genes." (PMID 29523784, 2018). "The novel zinc finger protein 121 (ZNF121) has been demonstrated to physically and functionally associate with the MYC oncoprotein to regulate cell proliferation and likely breast cancer development." (PMID 30524945, 2018). "The original study identified a relationship between MYC activation and 2-hydroxyglutarate (2-HG) accumulation as associated with poor prognosis in breast cancer." (PMID 29506475, 2018). "Recently, it has been reported that an association with the oncometabolite 2HG accumulations and MYC pathway activation in breast cancer patients." (PMID 29740540, 2018). "The most prominent long-range interactions in the region involve MYC, including those previously found to bring the breast cancer-associated variants in proximity with MYC." (PMID 30526553, 2018). "Of importance, the MYC-repressed TFs are tumor suppressors whose downregulation is strongly associated with poorly differentiated basal-like breast cancers." (PMID 29523784, 2018). "Chromatin looping from the 8q24 cancer risk-associated region to the MYC gene and MYC allelic imbalance have previously been implicated in the breast cancer-modulatory mechanism underlying the 8q24 locus." (PMID 30526553, 2018). "Taken together these data demonstrated that MYC-modulated enhancers activate oncogenic pathways, which are associated with basal-like breast cancer in patients with a poor prognosis." (PMID 29523784, 2018). "Analysis of 11 studies (16 cohorts) with 5390 breast cancer patients displayed that high MYC expression was associated with poor DFS/RFS, HR=1.500 (1.224-1.838)." (PMID 29212204, 2017). "A concomitant upregulation of TERT and MYC identified patients with a high risk of breast cancer recurrence." (PMID 29100407, 2017). "Particularly aggressive breast cancers were characterized by an association of TERT gains with MYC overexpression." (PMID 29100407, 2017). "More than half the cases reporting MYC amplification were from breast cancer (10 of the 18), where it has been reported to cause a highly aggressive form of the disease and has poor prognosis." (PMID 28371134, 2017). "In breast cancers, MYC de-regulation is associated with breast cancer development and poor prognosis." (PMID 29089515, 2017). "The same association was found between MYC expression and disease stage, which is in accordance with the results of a previous study in breast cancer patients." (PMID 28480695, 2017). "c-MYC and cyclin D1 are two major oncogenes, which confer proliferative and anti-apoptosis capacities to breast cancer cells, and are associated with altered sensitivity to endocrine therapy." (PMID 27465411, 2016). "MYC activation is a characteristic of basal-like breast cancer, the most common molecular subtype of TNBC and is associated with poor prognosis." (PMID 27486754, 2016). "We further used pooled samples to carry out DNA FISH for six genes previously reported to contribute to driver mutations in breast cancer: MYC, FGFR1, CCND1, HER2, TOP2A, and ZNF217." (PMID 26008969, 2015). "Six genes have been reported to contribute to about 44% of driver mutations in breast cancer (copy number increase or amplicons): MYC, FGFR1 (Chromosome 8); CCND1 (Chromosome 11); HER2, TOP2A (Chromosome 17); and ZNF217 (Chromosome 20)." (PMID 26008969, 2015). "Loss of BRCA1 coupled with MYC overexpression leads to the development of breast cancer and recent evidence has shown that MYC is druggable." (PMID 24550933, 2014). "Loss of BRCA1 with MYC overexpression leads to the development of breast cancer, especially, basal-like breast cancer." (PMID 23874497, 2013). "Overexpression of c-MYC gene is a signature of the majority of breast cancers, and there is a significant association between elevated levels of c-Myc and HPV 16 infection." (PMID 24138789, 2013).
breast cancer (continued). "We conclude that FBXO28 expression is positively correlated with increased expression of a subset of genes that are preferentially targeted by MYC in association with p300 in human breast cancer." (PMID 23776131, 2013). "MYC is known to be amplified in about 5% of breast cancers and associated with a more aggressive subtype and shortened survival." (PMID 22823888, 2012). "This region delimited from centromere to telomere by TRPS1 and PVT1 contains MYC, two colorectal cancer risk loci, rs16892766 (8q23.3) and rs6983267 (8q24.21), and one breast cancer risk locus rs13281615 (8q24.21)." (PMID 20932292, 2010). "MYC overexpression is commonly implicated in breast cancer and metastasis, and certain T-cell lymphomas overexpressing MYC possess specific hypermethylation signatures." (PMID 18638373, 2008). "Interestingly, MYC in a larger analysis of multiple studies has been less commonly found to be mutated in primary breast cancer than in other types of angiosarcoma." (PMID 41301029, 2025). "Like cyclin D1, c-MYC is an oncogene that regulates cell growth and cell proliferation at the G1 transition, and its amplification is associated with aggressive tumor behavior and poor outcome in patients with breast cancer." (PMID 39804138, 2025). "Additionally, elevated levels of 2HG are associated with the activation of the MYC pathway in breast cancer." (PMID 39408832, 2024). "MYC targets scores have also been associated with cancer aggressiveness in breast cancer." (PMID 36575316, 2023). "The presence of rs13281615 upstream of MYC is associated with a higher risk of breast cancer (BC)." (PMID 37443779, 2023). "Additionally, several studies have shown that MYC hyperactivation, a common feature in many human cancers, leads to transcriptional upregulation of splicing factors that direct breast cancer-associated AS switches promoting a malignant phenotype." (PMID 36725888, 2023). "While an increase of KDM3A is concomitant with a reduced H3K9me2/3 during breast tumorigenesis, KDM3A facilitated the activation of genes implicated in breast cancer as MYC, PAX3, Cyclin D1, MMP-9, S100A4, and JUN, thereby enhancing the proliferation and motility of breast cancer cells." (PMID 36185256, 2022). "c-MYC activity is associated with increased cell proliferation, tumor growth, and greater metastatic capacity, along with resistance to endocrine treatment in breast cancer, leading to a worse clinical outcome." (PMID 35053485, 2022). "In breast cancer, c-Myc overexpression may be sufficient to cause antiestrogen resistance, and MYC expression is upregulated by crosstalk between ER and HER2 in aromatase inhibitor-resistant breast cancer cells." (PMID 36059650, 2022). "MYC-mediated glutamine metabolism is associated with AI resistance in breast cancer." (PMID 36059650, 2022). "USP22-mediated deubiquitination of c-MYC is closely associated with breast cancer progression." (PMID 35935969, 2022). "Noteworthy, a recently proposed model of MYC-dependent signal transfer from breast cancer cells to the surrounding cancer-associated fibroblasts involves exosome-transported miR-105, which downregulates the expression of MXI1, an inhibitor of MYC activity, and results in an increased MYC activity." (PMID 36140779, 2022). "In breast cancer patients, MYC expression increased the risk of breast cancer brain metastasis." (PMID 35954348, 2022).
breast cancer (continued). "We previously reported a MYC-centered regulatory network in mouse embryonic stem (ES) cells that accounts for the similarity between the ES cells and cancer cells, and is associated with a worse prognosis in cancer, including cancers of the breast." (PMID 36207293, 2022). "Our results suggest that the efficacy of immune checkpoint inhibitor (ICI) therapy in TNBC and BRCA-mutated breast cancer may be restrained by MYC-induced suppression of local immune cells." (PMID 36323660, 2022). "Additionally, MYC is one of the widely studied oncogenes, and high MYC targets scores in breast cancer were associated with increased tumor immune cell infiltration." (PMID 35479936, 2022). "In accordance with the earlier findings that MYC-induced sumoylation is a therapeutic Achilles’ heel in B-cell lymphomas or that SAE1/UBA2 silencing causes synthetic lethality in MYC-amplified breast cancers, multiple MYC-expressing cancer cell lines are exceptionally hypersensitive to ML-792." (PMID 35269436, 2022). "For instance, repression of integrin expression by MYC in breast cancer cells has been linked to suppression of cell migration and metastasis, while another report suggests that Skp2 cooperates with MYC to induce RhoA transcription, thereby promoting metastasis." (PMID 36860495, 2022). "In luminal models, MYC appears to be involved in the regulation of metabolic pathways downstream of β-catenin and ERα signaling, thus associating the metabolic characteristics of intrinsic breast cancer subtypes on their ER expression." (PMID 33808259, 2021). "Copy number (CN) alterations in ctDNA were also associated with breast cancer subtype, with CN alterations in MYC, PIK3CA, EGFR, CCNE1, CDK6, BRAF and MET more common in TNBC (q = 0.01, q < 0.0001, q = 0.001, q < 0.0001, q = 0.0003, q = 0.0002 and q = 0.01, respectively)." (PMID 33893289, 2021). "However, breast cancer cells that exhibited resistance to olaparib were closely associated with PRMT1 or the MYC-targeted signature, specifically in TNBC cell lines." (PMID 34683150, 2021). "Herein, we showed that CCT2 expression can upregulate MYC and CCND1 gene expression and promote metastatic-like behavior in luminal A breast cancer cells that are typically less aggressive than the basal-like/TNBC subtypes usually associated with MYC amplification." (PMID 33996588, 2021). "However, ADHFE1 was identified as an MYC-linked oncogene that induces metabolic reprogramming and cellular de-differentiation in breast cancer." (PMID 34179501, 2021). "In addition to promoting cell proliferation, MYC overexpression has also been implicated in breast cancer cell stemness." (PMID 34066153, 2021). "It was speculated that SKA3 might be an upstream gene of MYC, and the high expression of SKA3 might activate MYC oncogene and promote tumor progression, which was associated with poor survival outcomes of breast cancer." (PMID 34993016, 2021). "In addition, CCT3 gene was positively associated with high expression of MYC in breast cancer, which was also consistent with our findings in Hallmark analysis." (PMID 34505628, 2021). "It was originally found to be associated with ovarian and breast cancer progression and reduced survival, and its silencing by short interfering RNA (siRNA) led to reduced growth and increased apoptosis in cell lines with MYC and PVT1 gain/overexpression." (PMID 34940760, 2021). "Given that higher MYC scores for both v1 and v2 were related to worse clinical and pathologic features, we expected there would also be an association between high MYC scores of the primary breast cancer and worse survival." (PMID 33143224, 2020). "Interestingly, the single-nucleotide polymorphism (SNP) “rs11780156,” which has been reported as a risk SNP in GWAS in breast cancer was found in the MYC enhancer E3." (PMID 33343635, 2020). "Mutations of the BRCA1 and MYC genes exacerbate breast cancer." (PMID 33324444, 2020).
breast cancer (continued). "BCAT1 being a c-MYC target has already been implicated in breast cancer." (PMID 32257110, 2020). "MYC is frequently amplified in breast cancer and amplification is associated with poor prognosis." (PMID 33176745, 2020). "Therefore, ATM deficiency in MYC overexpressed breast cancer will be expected to promote aggressive breast cancers." (PMID 30746633, 2019). "MYC overexpression has been linked to specific subtypes of aggressive breast cancers." (PMID 30746633, 2019). "Interestingly, a small number of losses were retained, including the Rb1-associated loss on chromosome 14, further supporting Rb1 as a collaborating driver in MYC-driven BRCA1-deficient mammary tumors." (PMID 30674894, 2019). "Furthermore, metadata analyses indicate that oncogenic pathways activated by MYC-regulated enhancers are associated with a poor prognosis of patients with basal-like breast cancers." (PMID 31013830, 2019). "Similarly, PVT1 has a very highly ranked enhancer cis-regulatory score, was also a CRISPRi hit in ENCODE breast cancer cell lines, and demonstrated to inhibit MYC expression in cis via promoter competition for common enhancer elements." (PMID 30767760, 2019). "In the current study, high ATR in MYC overexpressed tumours was linked to poor survival particularly in patients who received endocrine therapy providing further evidence for ATR as a predictive factor in MYC overexpressed ER+ breast cancers." (PMID 30746633, 2019). "MYC overexpression is seen in about 15% of breast cancers and linked to aggressive phenotypes." (PMID 30746633, 2019). "In breast cancer, deregulation of MYC is most frequent in basal‐like tumors and is associated with resistance to adjuvant chemotherapy; hence, targeting its dependent pathways could be a good therapeutic strategy." (PMID 30108112, 2018). "MYC amplification has been previously implicated in breast cancer." (PMID 30526553, 2018). "Jun DNA copy number loss, and/or high MYC signatures, might represent biomarkers for entinostat responsiveness in luminal breast cancer." (PMID 30497520, 2018). "To determine whether HN1 regulates MYC, we used quantitative real-time PCR and Western blot analysis to assess the expression of MYC and their targeted genes to determine the phenotype caused by knockdown of MYC in breast cancer cell with HN1 overexpression." (PMID 28490334, 2017). "Next, we asked whether SQLE or MYC expression could bear any association with survival in breast cancer patients." (PMID 26777065, 2016). "Importantly, nuclear ADA3 and c-MYC co-overexpression analyses define ER+ breast cancer subsets in which overexpression of c-MYC or loss of nuclear ADA3 independently predict poor survival." (PMID 27852327, 2016). "Interestingly, 2HG production was also found in breast cancer cells in association to MYC overexpression." (PMID 25849072, 2015). "In addition, CK1ε expression has been associated with c-MYC in several other tumors such as colon, lung, and breast cancer." (PMID 24904820, 2014). "Studies have already associated the gene desert locus of 8q24 with increased susceptibility for prostate, colorectal, and breast cancer; and subsequent molecular experiments have revealed a tissue-specific long-range cis-interaction between this region and the proto-oncogene MYC." (PMID 24376627, 2013).